FNDC3A (fibronectin type III domain containing 3A)
Description:
Mediates spermatid-Sertoli adhesion during spermatogenesis.
Synonyms: FNDC3; HUGO; KIAA0970; bA203I16.5; bA203I16.1
Tractability: Antibody: UniProt predicts a signal peptide or a membrane-spanning region. PROTAC: ubiquitination databases record sites on it; its protein half-life has been measured.
Gene: Protein-coding gene on chromosome 13 (48,975,912 to 49,209,779, forward strand). Ensembl gene ENSG00000102531.
Subcellular location: Golgi apparatus membrane
Subcellular location (Human Protein Atlas): Centrosome; Golgi apparatus; Nucleoplasm; Cytosol
Gene Ontology:
Molecular function: RNA binding
Biological process: spermatid development
Cellular component: Golgi apparatus; membrane; cytoplasm; acrosomal vesicle; cytoplasmic vesicle; cytosol; endomembrane system; Golgi membrane; vesicle membrane
Genetic constraint (gnomAD): Loss-of-function variants: 9 observed, 61.42 expected, observed/expected ratio (o/e) 0.15, 90% interval 0.087 to 0.26. The upper end of that interval is the gene's LOEUF score, 0.26, which puts it in group 1 of 6, group 1 being the genes least tolerant of losing a copy. Missense variants: 656 observed, 826.18 expected, observed/expected ratio (o/e) 0.79, 90% interval 0.74 to 0.85. Synonymous variants: 261 observed, 278.5 expected, observed/expected ratio (o/e) 0.94, 90% interval 0.85 to 1.04.
Homologues: Orthologues: chimpanzee FNDC3A (99% identical), macaque FNDC3A (99% identical), dog FNDC3A (95% identical), pig FNDC3A (95% identical), rabbit FNDC3A (94% identical), mouse Fndc3a (91% identical), rat Fndc3a (91% identical), guinea pig FNDC3A (91% identical), tropical clawed frog fndc3a (74% identical), zebrafish fndc3a (58% identical), Drosophila melanogaster mtgo (35% identical), Caenorhabditis elegans C34F6.10 (16% identical). Paralogues in human: FNDC3B (51% identical), MYOM1 (18% identical), MYOM2 (17% identical), MYOM3 (17% identical), MYBPC2 (15% identical), MYBPC3 (15% identical), MYBPC1 (14% identical), IGSF22 (14% identical), OBSL1 (13% identical), MYBPH (7% identical), MYBPHL (5% identical).
Diseases named in the same sentence as FNDC3A in open-access papers:
FNDC3A is named in the same sentence as 32 diseases in open-access papers, as found by Europe PMC text mining. Sharing a sentence is not in itself a finding about the gene and the disease. The quoted sentences say what the papers report.
breast cancer (4 papers, 2021 to 2024). A primary or metastatic malignant neoplasm involving the breast. "As a result, we propose that FNDC3A could be used as a predictive biomarker in the treatment of breast cancer, particularly in basal and luminal A subtypes." (PMID 36626432, 2022). "The lncRNAs may act as competing endogenous RNAs (ceRNAs) and interfere in the binding of miR-190b to certain targets such as ERG, STK38L, and FNDC3A and thus contribute to breast cancer pathogenesis." (PMID 33976257, 2021). "Furthermore, we developed a new biomarker, FNDC3A, for the prognosis of breast cancer, and lung adenocarcinoma might be able to choose the FNDC family as a prognostic biomarker." (PMID 36626432, 2022). "Few targeted genes of fs-cb-miRs like TNS1 (Cte-miR824-3p), UBE2K (Cte-miR168), FNDC3A (Cte-miR6183) and PAPD4 (Cte-miR7780-3p) were involved in malignant tumors of the breast, Alzheimer’s disease, Angelman syndrome and Hepatitis C virus infection, respectively." (PMID 38674383, 2024). "In contrast, higher FNDC3A, FNDC4, and FNDC5 predicted better survival for breast cancer patients." (PMID 36626432, 2022).
cervical cancer (3 papers, 2021 to 2023). A primary or metastatic malignant neoplasm involving the cervix. "The expression levels of FNDC3A, VEGFA, OPN3 and CPE were all high in cervical cancer tissues." (PMID 34630524, 2021). "Furthermore, we found that three of the signature genes (FNDC3A, VEGFA or CPE) function as oncogenes to promote the proliferation, invasion and migration of cervical cancer cells and could be potential therapeutic targets for CC." (PMID 34630524, 2021).
liver cancer (3 papers, 2013 to 2023). An epithelial or non-epithelial malignant neoplasm that arises from the liver. "With respect to liver cancer, high expression of FNDC1, FNDC3A, FNDC5, and FNDC7 was correlated with better prognosis, but increased expression of FNDC6 and FNDC8 was correlated with poor OS and PFS, respectively." (PMID 36626432, 2022). "Additionally, compared to normal liver tissues, FNDC3A and FNDC4 showed lower expression, while FNDC3B and FNDC8 displayed higher expression in liver cancer." (PMID 36626432, 2022).
colorectal cancer (2 papers, 2019 to 2021). A primary or metastatic malignant neoplasm that affects the colon or rectum. "FNDC3A can be used as a prognostic marker for colorectal cancer and is highly expressed in colon cancer tissues, and high expression of FNDC3A increases the mortality rate of colon cancer patients." (PMID 34630524, 2021). "We here aim to comprehensively analyze the mRNA expression of FNDC1, FNDC3A, FNDC3B, FNDC4, FNDC5, and GPR116 in nonaffected and affected mucosal samples of patients with IBD or colorectal cancer (CRC)." (PMID 31093274, 2019).
gastric cancer (2 papers, 2023 to 2025). A primary or metastatic malignant neoplasm involving the stomach. "Nevertheless, the role of FNDC3A in gastric cancer and its relationship with microRNAs need to be investigated." (PMID 40521987, 2025). "FNDC3A demonstrated elevated levels of expression in gastric cancer cells and tissues, with this heightened expression correlating to poor prognosis." (PMID 40521987, 2025).
multiple myeloma (2 papers, 2021 to 2022). "In multiple myeloma, high expression of FNDC3A can lead to ROS accumulation, ATP deficiency and cell death in multiple myeloma cells." (PMID 34630524, 2021). "For example, FNDC3A can bind FAM46C to inhibit multiple myeloma progression by regulating autophagy, and FNDC5 regulates the conversion of white fat to brown fat and improves insulin resistance by regulating the macrophage polarization, thereby reducing the validation response of adipose tissue." (PMID 36056336, 2022).
invasive breast carcinoma (1 paper, 2022). A carcinoma that infiltrates the breast parenchyma. "According to the Radvanyi and Finak databases, FNDC3A expression is elevated in both invasive mixed and invasive breast carcinomas." (PMID 36626432, 2022).
oesophageal adenocarcinoma (1 paper, 2014). "Two possible targets of this miRNAs are fibronectin type III domain containing 3A (FNDC3A), whose expression controls cell adhesion, migration and proliferation and myotubularin related protein 9 (MTM9), whose chromosomal gain is considered a prognostic event in oesophageal adenocarcinoma." (PMID 24866763, 2014).
ovarian carcinoma (1 paper, 2022). A malignant neoplasm originating from the surface ovarian epithelium. "In accordance with Bonome analysis, FNDC3A was downregulated in ovarian carcinoma." (PMID 36626432, 2022).
prostate tumors (1 paper, 2022). "In the Oncomine database, there are only 3 datasets for FNDC3A, FNDC4, and FNDC5, which indicate statistically notable distinctions between prostate tumors and normal tissues." (PMID 36626432, 2022).
squamous cell lung carcinoma (1 paper, 2022). A carcinoma arising from squamous bronchial epithelial cells. "Unfortunately, no gene, with the exception of FNDC3A, was found to be statistically significant in patients with squamous cell lung cancer." (PMID 36626432, 2022).
tumor (6 papers, 2016 to 2025). "FAM46C was shown to function as a tumor suppressor in MM by interacting with ER-bound protein FNDC3A." (PMID 40427516, 2025). "Our experimental procedures demonstrate that FNDC3A silencing can restore the tumour‐suppressive effects of miR‐206 on cell proliferation, migration and EMT." (PMID 40521987, 2025). "The qRT-PCR based panel of MYC, MYCN, CCND1, CCND2, EGFR and FNDC3A was successful in detecting neoplasia with an overall accuracy of 54 % in S-CRN compared to that of 29 % in UC neoplastic samples." (PMID 27080994, 2016). "This prevented the degradation of its target gene, FNDC3A, playing a tumour‐suppressive role in GC." (PMID 40521987, 2025). "After removing the tumour tissues, compared to the sh‐NC group, the tumours from the sh‐SNHG14‐1 group exhibited a decreased SNHG14 expression and elevated miR‐206 expression with a weakened FNDC3A expression." (PMID 40521987, 2025).
cancer (5 papers, 2022 to 2025). A tumor composed of atypical neoplastic, often pleomorphic cells that invade other tissues. "Once this is determined, it would be tempting to be able to stratify patients based on FAM46C/FNDC3A expression levels or mutational status, as this could enable us to predict cancer responsiveness to autophagy inhibitors and enable tailored and personalised therapies." (PMID 40001499, 2025). "Given that FNDC3A is also mutated in a fraction of MM patients and that its expression was shown to be associated with sensitivity to anti-cancer drugs in MM cell lines, here we tested if FNDC3A could have a role in FAM46C-induced sensitization to PF-543 administration." (PMID 40427516, 2025). "Multiple members, including FNDC1, FNDC3A, and FNDC3B, demonstrated significant expression changes between cancer and surrounding normal tissue groups in the malignancies studied in this study." (PMID 36626432, 2022). "Oncomine revealed that the mRNA expression levels of FNDC1, FNDC3A, and FNDC3B were higher in most malignancies than in normal tissues, but the mRNA expression levels of FNDC4, FNDC5, FNDC7, and FNDC8 were downregulated in most cancers when compared with normal tissues." (PMID 36626432, 2022).
adenocarcinoma (1 paper, 2016). A common cancer characterized by the presence of malignant glandular cells. "The functional significance of FNDC3A warrants further study in adenocarcinoma." (PMID 27080994, 2016).
blood cancers (1 paper, 2022). "Moreover, the expression of FNDC3A, FNDC3B, FNDC5, and FNDC6 has been implicated in the prognosis of blood cancers." (PMID 36626432, 2022).
FNDC3A also shares sentences with these, for which no sentence is quoted: Alzheimer disease (2 papers); and Central Nervous System cancer (1); Angelman syndrome (1); Anxiety (1); brain tumors (1); colon cancer (1); dementia (1); depression (1); hepatitis C virus infection (1); keratoconus (1); leukemia (1); lung adenocarcinoma (1); male infertility (1); melanoma (1); neurodegenerative disease (1); skin cancer (1); thalassemia (1).